ABTB2 (ankyrin repeat and BTB domain containing 2)
Description:
May be involved in the initiation of hepatocyte growth.
Synonyms: DKFZP586C1619; BTBD22; ABTB2A; CCA3
Tractability: PROTAC: ubiquitination databases record sites on it.
Gene: Protein-coding gene on chromosome 11 (34,150,987 to 34,358,010, reverse strand). Ensembl gene ENSG00000166016.
Subcellular location (Human Protein Atlas): Nucleoplasm; Vesicles
Gene Ontology:
Molecular function: protein binding; protein heterodimerization activity
Cellular component: nucleoplasm
Genetic constraint (gnomAD): Loss-of-function variants: 56 observed, 95.47 expected, observed/expected ratio (o/e) 0.59, 90% interval 0.47 to 0.73. The upper end of that interval is the gene's LOEUF score, 0.73, which puts it in group 3 of 6, group 1 being the genes least tolerant of losing a copy. Missense variants: 1,279 observed, 1,345.5 expected, observed/expected ratio (o/e) 0.95, 90% interval 0.91 to 1. Synonymous variants: 606 observed, 576.75 expected, observed/expected ratio (o/e) 1.05, 90% interval 0.98 to 1.12.
Homologues: Orthologues: chimpanzee ABTB2 (99% identical), macaque ABTB2 (99% identical), pig ABTB2 (98% identical), rabbit ABTB2 (97% identical), mouse Abtb2 (97% identical), rat Abtb2 (97% identical), dog ABTB2 (96% identical), tropical clawed frog abtb2 (77% identical), guinea pig ABTB2 (74% identical), zebrafish abtb2b (71% identical), zebrafish abtb2a (64% identical), Drosophila melanogaster lute (11% identical), and 3 more. Paralogues in human: ABTB3 (56% identical), KLHL11 (14% identical), BTBD3 (11% identical), BTBD6 (11% identical), BTBD2 (10% identical), BTBD1 (9% identical), BTBD9 (9% identical), ABTB1 (8% identical), SPOPL (7% identical), SPOP (7% identical), KBTBD4 (5% identical).
Diseases named in the same sentence as ABTB2 in open-access papers:
ABTB2 is named in the same sentence as 14 diseases in open-access papers, as found by Europe PMC text mining. Sharing a sentence is not in itself a finding about the gene and the disease. The quoted sentences say what the papers report.
astrocytoma (1 paper, 2022). "Validation of 6 biomarkers with the highest importance score in TCGA and CGGA cohorts revealed that HS3ST1, and CNN3 were overexpressed in astrocytoma, while SLAIN1, ABTB2, TRIM67 and DRG2 were overexpressed in oligodendroglioma." (PMID 35287567, 2022).
breast carcinoma (1 paper, 2020). "In conclusion, this study was the first to discover that patients with luminal A breast cancer carrying SNP rs6484711 variant A allele at ABTB2 5′UTR can significantly reduce the effectiveness of epirubicin combined with docetaxel by regulating the expression of ABTB2 protein." (PMID 33102228, 2020). "Furthermore, an eQTL analysis was performed to determine whether rs6484711 correlated with the mRNA expression levels of ABTB2 gene in luminal A breast cancer tumor." (PMID 33102228, 2020). "The relationship between ABTB2 and breast cancer has not been reported yet." (PMID 33102228, 2020).
gastric tumor (1 paper, 2010). "Although its specific function is unknown, one study has reported the up-regulation of ABTB2 in gastric tumor metastasis, highlighting the possible role of this gene in aggressive malignant phenotypes." (PMID 20459861, 2010).
Leukoencephalopathy (1 paper, 2010). This term describes abnormality of the white matter of the cerebrum resulting from damage to the myelin sheaths of nerve cells. "Downregulated genes included amyloid beta precursor protein‐binding, family a member 2 (APBA2); glycoprotein m6a (GPM6A); megalencephalic leukoencephalopathy with subcortical cysts 1 (MLC1); ankyrin repeat and btb domain containing 2 (ABTB2); and ring finger protein 43 (RNF43)." (PMID 19793339, 2010).
pancreatic ductal adenocarcinoma (1 paper, 2025). An infiltrating adenocarcinoma that arises from the epithelial cells of the pancreas. "Among them, the function of ankyrin repeat and BTB domain-containing protein 2 (ABTB2) in pancreatic ductal adenocarcinoma (PDAC), a highly lethal malignancy, has remained unexplored." (PMID 41322190, 2025).
Parkinson disease (1 paper, 2020). A progressive degenerative disorder of the central nervous system characterized by loss of dopamine producing neurons in the substantia nigra and the presence of Lewy bodies in the substantia nigra and locus coeruleus. "The protein encoded by the ABTB2 gene is ankyrin repeat and BTB/POZ domain-containing protein, which participates in the pathological process of Parkinson's disease by affecting the accumulation of α-synuclein." (PMID 33102228, 2020).
renal fibrosis (1 paper, 2024). A final common manifestation of a wide variety of chronic kidney diseases characterized by glomerulosclerosis and tubulointerstitial fibrosis. "We hypothesize that APC and ZBTB2 are closely associated with M2 macrophage infiltration, and uncovering the role of APC and ABTB2 in M2 macrophage infiltration may unravel the physiopathological mechanisms underlying the development of renal fibrosis." (PMID 39328595, 2024).
tumor (3 papers, 2020 to 2025). "Our gain- and loss-of-function studies revealed that ABTB2 plays a pivotal tumor-suppressive role, significantly impairing PDAC cell oncogenicity in vitro and tumorigenesis in vivo." (PMID 41322190, 2025). "Collectively, our findings indicate that gain and loss of ABTB2 function significantly affect PDAC tumor development and recipient mice survival, involving modulation of tumor cell viability and apoptosis." (PMID 41322190, 2025). "Our findings not only highlight ABTB2 as a promising molecular target in PDAC but also shed light on a novel tumor-suppressive mechanism mediated by TRAP1." (PMID 41322190, 2025). "For ITGA2, SLC1A5, TIAM1, TNIK, and ABTB2, several studies showed that their high expression played a significant role in promoting tumor cell growth and inhibiting cell apoptosis from chemotherapy in different kinds of cancers." (PMID 35267472, 2022). "Using these cells and the derived orthotopic models, our comprehensive experiments demonstrated that ABTB2 function, either through gain or loss, profoundly impacts key PDAC cellular processes, including cell proliferation, migration, and apoptosis as well as in vivo tumor development." (PMID 41322190, 2025). "Given ABTB2’s critical role in PDAC cellular events in vitro, we explored its impact as an intrinsic factor on PDAC tumor growth in vivo." (PMID 41322190, 2025). "Overall, recombinant ABTB2 exerts therapeutic effect on both mouse and human PDAC tumors by suppressing tumor cell proliferation, inhibiting vascularization, and promoting tumor apoptosis, highlighting its potential clinical application for the treatment of human PDAC." (PMID 41322190, 2025).
cancer (2 papers, 2022 to 2025). A tumor composed of atypical neoplastic, often pleomorphic cells that invade other tissues. "However, only two papers have investigated ABTB2’s role in cancers." (PMID 41322190, 2025). "Despite this, ABTB2 remains entirely uncharacterized in PDAC, one of the most treatment-refractory and molecularly distinct cancers." (PMID 41322190, 2025).
ABTB2 also shares sentences with these, for which no sentence is quoted: arterial hypertension (1 paper); Luminal A (1); oligodendroglioma (1); pancreatic cancer (1); thyroid cancer (1).